CXCL12 (C-X-C motif chemokine ligand 12)
Diseases named in the same sentence as CXCL12 in open-access papers (continued):
Sharing a sentence is not in itself a finding about the gene and the disease.
tumor (continued). "The stromal cell-derived factor-1 (CXCL12/SDF-1) facilitates the accumulation of neutrophils expressing high levels of CD15 in CRC tumors, in which case, CD8+ T cells produce high levels of Granzyme K, subsequently diminishing E-cadherin on the intestinal epithelium and promotes tumor progression." (PMID 40092983, 2025). "Furthermore, CAFs may alter the anti‐tumor immune response through secretion of several immune modulators such as IL6, CCL2, CXCL12, and TGFβ2, which we found to be up‐regulated in CMS4 PM." (PMID 39739693, 2025). "Additionally, APS may interfere with the CXCR4/CXCL12 (SDF-1) chemokine axis, reducing Treg infiltration into tumour sites and consequently enhancing antitumour immune responses." (PMID 40649307, 2025). "MSC recruitment to tumor sites is facilitated through numerous factors secreted by stroma, including growth and angiogenic factors (PDGF, FGF, VEGF, SDF, HGF), chemokines, and inflammatory cytokines (CCL2, CCL5, CCL22 and CXCL12, TNFα, TGFβ, IL-1β, IL-6, IL-8)." (PMID 40723180, 2025). "Additionally, CXCR4/CXCL12 signalling enhances CSC populations to mediate resistance by retaining a portion of quiescent, drug-tolerant cells, which are capable of repopulating the tumour after treatment is paused." (PMID 41002447, 2025). "Similarly, after co-incubation with PLIGHT- or PαCD3&LIGHT-transfected tumor cells, the mRNA levels of chemokines and vascular adhesion molecules in vascular endothelial cells, such as CXCL-2, CXCL-8, CXCL-12, CCL-21, MADCAM-1, and VCAM-1, rose by about 2- to 5-fold." (PMID 41406950, 2025). "Additionally, CXCL12 is involved in angiogenesis by recruiting endothelial progenitor cells and increasing vascular endothelial growth factor (VEGF) expression, thereby promoting tumor vascularization." (PMID 40481962, 2025). "Moreover, GPR176 may influence the immune status of the tumor microenvironment in STAD by regulating the immunosuppressive function of TGFB1 and the chemotactic activity of CXCL12, further affecting tumor progression." (PMID 40689396, 2025). "In addition to structural impediments, CAFs contribute to spatial immune exclusion through the secretion of chemokines such as CXCL12, which activates the CXCR4 signaling axis and creates a chemotactic barrier that restricts immune cell localization to the tumor periphery." (PMID 41341574, 2025). "ENKTCL-derived or tumor-educated MSCs can produce a range of growth factors and extracellular matrix components that facilitate tumor cell proliferation, invasion and survival, such as VEGF, hepatocyte growth factor (HGF) and stromal-derived factor 1 (SDF-1/CXCL12)." (PMID 41303704, 2025). "In addition, endothelial cells of large vessels in the tumor stroma also overexpressed the CXCR4 receptor, suggesting that the CXCR4/CXCL12 axis may be highly involved in tumor angiogenesis." (PMID 40142155, 2025). "CD36 also exhibited positive correlations with several immunostimulators, including C10orf54, CXCL12, ENTPD1, CD28, and TNFSF18, suggesting that it may contribute to immune activation pathways and modulation of antitumor immune responses in the tumor microenvironment." (PMID 41550652, 2025). "Similarly, tumor cells can secrete chemokines such as CXCL12, VEGF, and CXCL8/IL-8, attracting mast cells into the TME, where they become activated and release cytokines, chemokines, and angiogenic factors, further driving tumor progression." (PMID 40438115, 2025). "TAMs regulate angiogenesis in the tumor microenvironment through the release of pro-angiogenic substances vascular endothelial growth factor (VEGF), basic fibroblast growth factor (bFGF), and chemokines (CXCL8 and CXCL12), and anti-angiogenic substances like TSP-1." (PMID 38185636, 2024). "Moreover, CXCL12 released by TECs and BoxA, a fragment of HMGB1, can engage the CXCR4-CD47 complex and trigger CD47 internalization to release a phagocytosis signal by the tumor cells and attract macrophages." (PMID 38726320, 2024).
tumor (continued). "CXCL12 bound to its specific G protein-coupled receptor CXCR4 induces a plethora of downstream signaling events involving ERK1/2, RAS, PLC/MAPK, p38 MAPK, and SAPK/JNK, which are in turn responsible for various biological and pathological processes including angiogenesis and tumor metastasis." (PMID 38182756, 2024). "Notably, CXCL12 stimulated the AKT/NF-κB pathway, whereas CXCL12 neutralizing attenuated the stimulation, indicating CXCL12 mediated AKT/NF-κB pathway activation by iCAFs, EMT is a critical step for tumor metastasis." (PMID 39759028, 2024). "Furthermore, the CXCL12/CXCR4 has been recognized as a prognostic marker in different cancers and preclinical models; signifying that metastasis is mediated by CXCR4 activation and migration of tumor cells towards CXCL12 expressing organs." (PMID 38877052, 2024). "C-X-C Motif Chemokine Ligand 12 (CXCL12), a ligand for the G-protein-coupled receptors chemokine (C-X-C motif) receptor 4 (CXCR4) and CXCR7, plays a role in many diverse cellular functions, including embryogenesis, immune surveillance, inflammation response, tissue homeostasis, and tumor growth." (PMID 39795953, 2024). "Therefore, GGT5 may exert a pro-tumor effect by regulating immune genes such as CXCL12 and CXCL4 in the tumor microenvironment." (PMID 38748299, 2024). "In a murine breast cancer model, tumor-draining lymph node-resident B cells, after being cultured ex vivo and then reinfused, could directly eradicate tumor cells via mechanisms involving CXCR4/CXCL12 and perforin." (PMID 39519376, 2024). "Furthermore, CXCL12-deleted mice reduced leukemic cells expansion and tumor burden, and no splenomegaly or thymic infiltration compared with the control group 88." (PMID 37497001, 2023). "For instance, CXCL12 generation by activated CAF in PDAC increases migration of peripheral CD8+ T cells to active CAF in the peritumor stromal region, resulting in a concentration of CD8+ T cells in the pan-mesenchymal compartment and decreased recruitment to the tumor islets." (PMID 37007004, 2023). "In addition, CXCL12, cancer cells secrete the chemokine-like protein osteopontin (OPN), and OPN-driven CAFs then secrete CXCL12, which in turn triggers modification of the EMT in tumor cells." (PMID 37978384, 2023). "Addition of CXCL12 neutralizing antibodies did not affect CD26+ NF-induced tumor cell invasion." (PMID 36635273, 2023). "Additionally, chemokine CXCL12 regulates cell adhesion, promotes communication between neoplastic cells and non-malignant cells in the tumor microenvironment, and activates tumor-infiltrating immune cells, such as macrophages and neutrophils." (PMID 37511619, 2023). "Moreover, CXC ligand 12 (CXCL12, also called stromal cell-derived factor-1, SDF-1), which is produced by stromal cells and binds to C-X-C chemokine receptor type 4 (CXCR4) on the surface of tumor cells, has been reported to be essential for cancer pathogenesis." (PMID 37173977, 2023). "Interestingly, CAFs promote tumor growth, angiogenesis, immunosuppression, and metastasis via the secretion of growth factors such as VEGF, TGF-β, cytokines and chemokines (IL-6, CXCL12), PDGF, and MMPs." (PMID 37686315, 2023). "In addition, the CXCL12/CXCR4 axis may also promote cell proliferation, tumor growth, and angiogenesis." (PMID 37227446, 2023). "It is therefore possible that CXCL12 secreted by muscle cells may functionally affect OSCC cells, though it remains unclear whether the muscle cell‐derived CXCL12 contributes to or inhibits tumor progression." (PMID 36300800, 2023). "Then, we focused on the tumor cell and lymphocyte interactions mediated by chemokines and demonstrated that mTEC-like and mcTEC-like tumor cells in TETs could induce DP cell migration for positive selection through CCL25:CCR9 and CXCL12:CXCR3 interactions." (PMID 36115836, 2022).
tumor (continued). "The observed combined effects of CXCL12 and CXCL11 on cell migration prompted us to determine further whether similar applies for cell invasion, a process more closely reflecting metastatic behavior of tumor cells." (PMID 36539774, 2022). "Recently, it has been demonstrated that hybrid E/M cells induce the formation of a tumor-promoting microenvironment through the upregulation of potent immunosuppressive proteins, including PD-L1, CD73 (5′-NT), CD276 (B7-H3), CSF1 (M-CSF), SPP1, galectin-3, MASP1, and SDF1 (CXCL12)." (PMID 36467417, 2022). "Interestingly, synergistic effects of CXCL12 and CXCL11 on cell migration were only detectable in tumor cells in which CXCL11-dependent cell migration was sensitive to the p38 inhibitor, SB203580 (A549, A767), and in which CXCL11 and CXCL12 affected cell migration via different signaling pathways." (PMID 36539774, 2022). "In addition, CAFs secrete cytokines like CCL7, CXCL12, and CXCL14 that favour tumour progression." (PMID 36555218, 2022). "We demonstrated that the mouse PDA tumor was a suitable model for this analysis by showing that the KRT19+ cancer cells in subcutaneous (s/c) PDA tumors were coated with CXCL12, as assessed by imaging nonpermeabilized sections that had been stained with antibodies to KRT19 and CXCL12." (PMID 35046049, 2022). "At the tumor site, BMDSCs also have the capacity to differentiate into angiogenesis-promoting endothelial cells, or TAFs as a source of extracellular protease expression, TGF-β, VEGF, CXCL-12, -14, -16, CCL2-5, IL-4 or IL-6, the collective interplay of which contributes to tumor progression." (PMID 34918208, 2022). "For example, targeting CXCL12 with Pleraxifor, a C-X-C chemokine receptor type 4 (CXCR4) inhibitor, was shown to induce rapid T-cell accumulation among cancer cells and act synergistically with antibodies against Programmed death-ligand 1 (PD-L1), resulting in a strong reduction of tumor cells." (PMID 35892828, 2022). "Furthermore, CAF-secreted CXCL12 recruits more CXCR4 expressing cells, like endothelial cells, epithelial cells and immune cells to activate intracellular pathways leading to cell proliferation and tumor progression." (PMID 35565443, 2022). "The rapid proliferation of tumor cells leads to tumor ischemia and hypoxia, which directly stimulates angiogenesis and promotes the secretion of cytokines such as matrix metalloproteinase-9 (MMP9), C-X-C motif chemokine ligand 12 (CXCL12) and Wnt7B by various cells, especially tumor cells." (PMID 35454769, 2022). "Consequently, blocking the interaction of CXCL12/CXCR4 using neutralizing antibodies or targeting the expression of CXCR4 via RNAi/CXCR4 suppressed both regional and distant metastasis and prevented tumours growth in vivo." (PMID 36510219, 2022). "In addition, unlike plerixafor, it is ableto induce apoptosis in CD19+ tumor B cells, interferingwith CXCL12-induced migration by acting as a potent inhibitor of cellchemotaxis." (PMID 38239337, 2022). "Studies suggest that the CXCL12 axis is a promoter rather than a tumor initiator." (PMID 35406582, 2022). "Therefore, while this antagonist has proved effective in controlling tumor progression in various cancers, these observations suggest caution in its use to understand the respective roles of CXCR4 and CXCR7 as mediators of the biological effects of CXCL12." (PMID 35406582, 2022). "Moreover, in none of the tumor cells, gelatinase expression was affected by CXCL12 and/or CXCL11, implying that gelatinases do not account for co-operative effects of these chemokines on tumor cell invasion." (PMID 36539774, 2022). "Therefore, CXCL12 promotes communication between cancer cells and the surrounding non-neoplastic cells in the tumor microenvironment, including endothelial cells and fibroblasts, through activation of CXCR4 and CXCR7." (PMID 35406582, 2022).
tumor (continued). "Furthermore, radiation selectively induced CXCL12, CXCR4 and FAPα expression in tumor tissues." (PMID 34976180, 2022). "Furthermore, the interaction between CXCL12 on LECs and CXCR4 on invading tumour cells may also promote metastasis to lymph nodes." (PMID 35072206, 2022). "When examining the factors that could contribute to CD8+ Teff tumor recruitment, we found that CD8+ Teffs expressed the chemokine receptors CXCR3 and CXCR4, while the TME produced abundant CXCL9 and CXCL12, which are the key chemokines known to bind CXCR3 and CXCR4, respectively." (PMID 35552271, 2022). "Certainly, for its formation and progression, GBM cells engage different chemokines such as CXCL8, CXCL16, CX3CL, CCL5, CXCL12, and their receptors CXCR1-2, CXCR6, CX3CR1, CCR5, CXCR4-7, respectively, for a chemokine network communication mechanism to maintain and increase the tumor malignancy." (PMID 35745762, 2022). "CAFs in GC have been found to secrete cytokines, such as CXCL12, interleukin 11 (IL-11), stromal-derived factor 1 (SDR1), and fibroblast growth factor 9 (FGF-9), to promote epithelial–mesenchymal transition (EMT), the key initiator of tumor invasion and metastasis." (PMID 35557959, 2022). "Specifically, CXCL12 is dominantly secreted by CAFs and excludes T cells from the tumor region." (PMID 36230914, 2022). "In addition, RT-induced TGF-β signaling increases the number of CAFs whose release of CXCL12 binds to the ligands CXCR4 and CXCR7, exerting pleiotropic pro-tumor activity, including induction of tumor survival, metastasis and affecting immune cell infiltration, and function." (PMID 36532071, 2022). "Fittingly, CXCL12 methylation downregulates tumor intrinsic CXCL12 protein expression, disrupting cellular feedback mechanisms to internalize membranous CXCR4 in PCa, thereby fostering metastasis, which is suggestive of the possible therapeutic potential of CXCL12 inhibitors." (PMID 35406450, 2022). "For example, stromal-derived factor 1 (SDF-1/CXCL12) secreted by CAFs promotes bone metastasis by interacting with cancer cells through CXCR4, while CAFs-secreted epidermal growth factor receptor (EGFR) can promote bone metastasis by directly interacting with tumor cells." (PMID 36237303, 2022). "CXCL12 plays a key role in cancer progression by binding directly to CXCR4 expressed on cancer cells, promoting proliferation and invasiveness and indirectly by recruiting tumor immunosuppressive cells or by sequestering T cells in the tumor stroma as shown in several PDAC studies." (PMID 35954489, 2022). "Finally, CXCR4 signaling, where TNC induces CXCL12 in tumor cells (through TLR4), but also binds to CXCL12 (again in the TN3–TN5 domains) thus trapping CD8T cells in the stroma, exerting a Janus function (i.e. both activation and inhibition) on yet another pathway." (PMID 36102918, 2022). "Among tumor-related factors involved in the generation of MDSCs and their recruitment from bone marrow to tumor microenvironment are mediated by granulocyte–macrophage colony-stimulating factor (GM-CSF), IL-6, indoleamine 2,3-dioxygenase (IDO) and chemokines (e.g. CCL26, CXCL12, CXCL8)." (PMID 35589776, 2022). "A combined on-tumor and off-tumor inhibition of HIF-1α was also observed in idelalisib-treated patients, who showed, along with a downregulation of HIF-1α target genes in leukemic cells, a significant decrease in CXCL12 serum concentration and changes in the bone marrow microenvironment." (PMID 34207596, 2021). "High CXCL12 levels, potentially acting as protective shield toward CD8 TIL (by an unknown mechanism), may even further potentiate CD8 TIL exclusion from the tumor nest." (PMID 33988305, 2021).
tumor (continued). "Reduced CXCL12 levels in an orthotopic tumor model using the murine ovarian cancer cell line ID8-T changed the composition of the immune cell population within tumors, reducing myeloid cells, plasmacytoid dendritic cells and Tregs, while increasing IFN-γ+/IL10+ tumor-infiltrating T lymphocytes." (PMID 33530455, 2021). "Notably, the pre-treatment of NK-92 cells with PGE2 did not impair migration or cytotoxic potential independent of CXCL12 supplementation of tumor medium." (PMID 33925968, 2021). "Indeed, genetic CXCL12 deletion or pharmacological inhibition of CXCR4 partially prevents BrCa and PrCa metastasis to lungs and bones as well as early steps of intraosseous tumor growth." (PMID 34064859, 2021). "Several studies have also shown that high doses of anti-angiogenic agents could lead to hypoxia of the tumor microenvironment and upregulation of the CXCR4/CXCL12 axis and HIF-α levels due to excessive pruning of tumor vessels, which facilitates the recruitment of TAMs, MDSCs, and Tregs." (PMID 33746989, 2021). "Studies on tumor cell biology indicated that the interaction between C-X-C motif chemokine receptor 4 (CXCR4) and its chemokine ligand 12 (CXCL12; also known as stromal cell-derived factor 1, SDF-1) plays an essential role in cell oncogenesis and development of metastatic lesions in tumor." (PMID 34070538, 2021). "Moreover, targeting CXCR4 or CXCR7 alone is not sufficient for inhibiting CXCL12-mediated pro-metastatic responses suggesting that compensatory pathways induced by these receptors can allow tumor escape." (PMID 34298991, 2021). "CAFs and tumor cells need reciprocal communication to stimulate mediators such as vimentin, matrix metalloproteinase (MMPs); periostin; Insulin growth factor-2 (IGF2); IL-33; and CXCL12, related to and tumor growth, invasion, and downregulation of tumor suppressor genes." (PMID 34204259, 2021). "CAFs directly stimulate cancer cell growth and also enhance tumor angiogenesis by paracrine signaling, such as vascular endothelial growth factor (VEGF), hepatocyte growth factor (HGF), growth differentiation factor 15 (GDF15), C-X-C Motif Chemokine Ligand 12 (CXCL12) and CXCL14." (PMID 34681633, 2021). "In conclusion, our results suggest that the MSC-derived CXCL12 niche is involved in macrophage polarization dynamics as it could prompt BMDM phenotypic switching into M2 macrophages, which could have a decisive role in the tumor microenvironment." (PMID 34174813, 2021). "Numerous signaling molecules, including stromal derived factor-1 (SDF-1/CXCL12), transforming growth factor-β (TGF-β), interleukin-8 (IL-8), matrix metalloproteinase-1 (MMP-1), and monocyte chemoattractant protein 1 (MCP-1/CCL2) were shown to be involved in MSC recruitment to the primary tumor site." (PMID 33287630, 2021). "In fact, the level of CXCL12 is increased in non-involved BM plasma suggesting that FL EVs could shape the BM stromal niche before BM infiltration by tumor cells or at distance from this BM infiltration (unpublished data)." (PMID 34956214, 2021). "MiR-125b-5p seems to function both as a tumor suppressor miR in induced L-OHP-resistant HCT8 cells, or conversely as an oncomiR (oncogenic miR) when it is upregulated in HCT116 and SW620 cell lines in response to treatment with C-X-C motif chemokine ligand 12 (CXCL12), leading to chemoresistance." (PMID 33429840, 2021). "M2-like macrophages promote tumor angiogenesis by producing proangiogenic growth factors (VEGF-A, epidermal growth factor (EGF), and fibroblast growth factor (FGF)), proangiogenic CXC chemokines (CXCL8/IL-8 and CXCL12), and angiogenesis-related factors (TGF-β and TNF-α)." (PMID 34294146, 2021). "Although we did not observe the inhibition of tumor cell migration by an anti-CXCL12 antibody we tested (data not shown) we could not rule out the role of CXCL12 in hypoxic condition." (PMID 34093792, 2021).